ALB (albumin)
Diseases named in the same sentence as ALB in open-access papers (continued):
Sharing a sentence is not in itself a finding about the gene and the disease.
kidney disease (continued). "According to our results, abnormal temperature (≤36.0 or ≥38.5 °C), chilling, kidney disease, the etiology of drug reactions, elevated CRP (≥32 mg/L) and PCT (≥1.00 ng/ml), and low ALB (≤31.0 g/L) could be fingered as the predictors of BSI." (PMID 39006018, 2024). "Third, our study did not fully consider other health conditions affecting albumin levels such as kidney disease, and these factors will need to be considered in future studies." (PMID 38409895, 2024). "Moreover, the biomarkers related to kidney disease in plasma measured in the CCD group, such as blood urea nitrogen, total protein, and albumin, were also significantly higher than those in the ND group." (PMID 37762074, 2023). "UACR: urinary albumin to creatinine ratio; ISKDC: International Study for Kidney Disease in Children Classification; DMARDs: disease modifying anti-rheumatic drugs; DMARDs used in this cohort: hydroxychloroquine, mycophenolate mofetil, azathioprine; eGFR: estimated glomerular filtration rate." (PMID 38046006, 2023). "The Kidney Disease: Improving Global Outcomes (KDIGO) guideline categorizes albuminuria into microalbuminuria (spot urine albumin-to-creatinine ratio; uA/Cr 30–300 mg/g) and macroalbuminuria (uA/Cr > 300 mg/g) based on the extent of albumin excretion." (PMID 38140298, 2023). "High urinary albumin may indicate progressive CVD and kidney disease among diabetic patients, which could explain the association between microalbuminuria and increased risk of mortality." (PMID 35807807, 2022). "A significant number of T2DM patients with impaired renal function do not present preceding albuminuria (30–40%), and, inversely, those with elevated albumin do not always develop renal disease." (PMID 36011513, 2022). "Urinary albumin and protein are other biomarkers, although they are not frequently recognized or employed since they can both indicate and even contribute to renal disease." (PMID 36415443, 2022). "It is worth mentioning that some centres still do not utilize urinary albumin/protein for screening for kidney disease which is required by EACS guidelines." (PMID 36231850, 2022). "Mild histological and biochemical manifestations of kidney disease are found primarily in the tubulointerstitial compartment as a result of albumin overload, and these do not appear to be ameliorated by TRPC6 inactivation." (PMID 35805070, 2022). "In 2012, Kidney Disease: Improving Global Outcomes (KDIGO) proposed CKD staging criteria based on the estimated glomerular filtration rate (eGFR) and urinary albumin levels because eGFR levels and the urinary albumin/creatinine ratio are both correlated with poor prognosis." (PMID 35928297, 2022). "Serum albumin was lower in the proteinuria group vs. controls without kidney disease (n = 159; 2.9 mg/dl vs. 4.6 mg/dl; p < 0.001)." (PMID 33575899, 2021). "According to the guidelines of National Kidney Foundation‐Kidney Disease Outcomes Quality Initiative (NKF KDOQI), DKD was divided into microalbuminuria (albumin/creatinine ratio, ACR 30‐300 mg/g) and macroalbuminuria (ACR > 300 mg/g) based on the level of albuminuria." (PMID 33369170, 2021). "Recently, some studies showed that there was an important link between albumin and the mitogen-activated protein kinase (MAPK) extracellular signal-regulated kinase, ERK1/ERK2 in kidney disease, and ERK1/2 signaling pathway was the downstream signal activated by albumin therapy." (PMID 33708336, 2021). "Serum albumin is an indicator and predictor of poor nutritional status in kidney disease, moreover, it is a known negative acute phase protein." (PMID 33375581, 2020). "In addition to acting as a fatty acid translocase, CD36 also functions as a novel mediator influencing binding and uptake of albumin in the proximal tubule, and CD36 is upregulated in proteinuric renal diseases." (PMID 30934807, 2019).
kidney disease (continued). "On the other hand, blood viscosity has been associated with decreased renal function and increased urinary excretion of albumin in hypertensive patients without renal disease." (PMID 30937231, 2019). "Raised albumin–creatinine ratio (ACR) is an indicator of microvascular damage and renal disease." (PMID 31630189, 2019). "Therefore, age, sex, basal kidney disease, dialysis vintage, current smoking, past CVD, albumin, DW at enrollment, serum creatinine, mean predialysis SBP, and CTR were applied to Cox regression analysis as confounders." (PMID 30148875, 2018). "The subgroup with DR and/or DN also had more evidence of renal disease reflected as increased albumin-to-creatinine ratio in comparison with those without DR and/or DN." (PMID 30648112, 2018). "Though limiting because no human renal disease presents as such, this unique model permitted us to clearly study the effects of urinary albumin on renal transporter expression." (PMID 29100270, 2017). "In the present study, 47 patients had detectable levels of IgM, while only 21 patients had albuminuria; thus, renal disease was found in patients not detected by analysis for urine albumin." (PMID 22400116, 2012). "The exact mechanism by which this transpires in unclear, but it could be attributed to the systemic inflammatory state in kidney disease, where albumin is a negative acute phase reactant." (PMID 41295863, 2025). "Other than serum albumin, Factor 1 did not exhibit a direct relationship to kidney disease." (PMID 38347632, 2024). "The diagnosis of CKD was based on a single eGFR assessment, without albumin testing, which may tend to overestimate the incidence of kidney disease." (PMID 37679536, 2023). "Accordingly, the Kidney Disease: Improving Global Outcomes (KDIGO) clinical practice guidelines stage CKD severity by categories of eGFR (≥60, 45-59, 30-44, and < 30 ml/min/1.73m2) and albuminuria (urine albumin/creatinine ratio [UACR] < 30, 30-299, and ≥ 300 mg/g)." (PMID 36434513, 2022). "Urine albumin was not measured, but albuminuria is an early sign of renal disease." (PMID 35712088, 2022). "The amounts of albumin and RBC in urine also could be good indicators of kidney disease." (PMID 34607566, 2021). "Third, it would be better to use urine albumin to creatinine ratio (ACR) to identify kidney disease instead of urine routine test of protein since urine ACR has greater sensitivity for low levels of proteinuria and improves the detection of kidney disease in the study population." (PMID 33430940, 2021). "However, the albumin:globulin ratio and glomerular filtration rate, which are the most important markers for kidney disease, were not assessed." (PMID 34588483, 2021). "This is unsurprising as the ISN survey showed that only 30% of LMIC had access to health technologies like measurement of serum creatinine and urine albumin testing, none had access to eGFR and quantitative estimation of albuminuria, and low availability of essential medications for kidney disease." (PMID 31996168, 2020). "Third, serum creatinine values were only obtained in participants who had urine studies positive for albumin so we may have missed participants with non-proteinuric kidney disease and underreported the prevalence of kidney disease in this screening cohort." (PMID 30359229, 2018). "However, normalization of data to either urinary creatinine or albumin, which would be increased in many renal diseases, did not affect the results." (PMID 19057641, 2008). "The hypothesis that low serum albumin reflects an inflammatory state, which contributes to progression of kidney disease is supported by recent studies in both non-diabetic and diabetic populations." (PMID 15985177, 2005).
kidney disease (continued). "ALB was usually associated with HSP renal disease, and the relationship with HSP GI bleeding was not clear, but some severe GI bleeding would present with reduced ALB and even require ALB supplementation, suggesting that reduced ALB may be of some value in identifying the presence of GI bleeding." (PMID 36248897, 2022). "In all groups, urinary albumin/creatinine ratios were similar (data not shown) and within the normal range suggesting that the experimental diets had not yet affected the filtration function of the kidneys and that the present data reflect an early stage of renal disease." (PMID 21483792, 2011). "We compared the renal parameters like serum urea, creatinine, sodium, potassium, urine albumin, creatinine, urine ACR, eGFR, and urine MMP-7 levels among the participants with or without T2DM and kidney disease." (PMID 39246865, 2024). "DM patients were divided into three subgroups (Group-DI/DII/DIII, based on urinary albumin-creatinine ratio (UACR)) and a nondiabetic kidney disease group (Group-NDKD)." (PMID 36210998, 2022). "However, this is important information as monitoring albumin-to-creatinine ratio or protein-to-creatinine ratio in a child with previous AKI is a simple investigation, less invasive than serial serum creatinine measurements, and may detect early kidney disease in this population." (PMID 33791260, 2021). "Finally, although total protein, albumin, creatinine, urea and uric acid levels differed between the groups (P < 0.001), they were within the reference range for these parameters and none of the subjects exhibited clinical symptoms of kidney disease or others pathologies." (PMID 28699988, 2017). "DN is characterized by the appearance of persistent clinical albuminuria (albumin excretion rate (AER) > 300 mg/24 h) and a reduction in the glomerular filtration rate (GFR) > 5 years in the absence of urinary tract infections, other kidney diseases, or cardiac insufficiency." (PMID 29808088, 2018). "In addition, several gold standard investigations for HIV and kidney disease, such as quantitative HIV viral load testing, urine albumin-to-creatinine ratio, and kidney biopsies were not performed since they were not available in our region at the time of the study." (PMID 25612312, 2015).
cardiovascular disease (549 papers, 2007 to 2026). "The prognostic significance of serum albumin in cardiovascular diseases stems principally from its associations with nutritional status and systemic inflammation." (PMID 41561116, 2025). "Previous studies have also shown that low serum ALB is associated with cardiovascular disease, which results in loss of antioxidant capacity as well as anticoagulant and antiplatelet activity." (PMID 40153388, 2025). "This research aims to understand the association between serum albumin and urinary albumin levels among individuals with cardiovascular diseases (CVDs) at a tertiary healthcare facility." (PMID 41536368, 2025). "These combined effects lead to a decrease in ABL, and a lower ALB has been demonstrated to be linked to an elevated risk of cardiovascular diseases; Thirdly, an elevated RAR level is likely to be associated with alterations in cardiac structure and function." (PMID 40271132, 2025). "Most potentially causal metabolite–disease pairs were found in metabolic and cardiovascular diseases, with the well-known bidirectional causal relationship between albumin level and CKD38,39." (PMID 40973818, 2025). "Low serum albumin level is associated with cardiovascular disease and is an independent marker of adverse cardiac events." (PMID 41517395, 2025). "Increasing evidence suggests that low ALB levels indicate a state of heightened inflammation, which is closely linked to the development and prognosis of various cardiovascular diseases." (PMID 40357038, 2025). "Background and Objectives: The neutrophil-percentage-to-albumin ratio (NPAR) has been recognized as an independent risk factor for cardiovascular diseases." (PMID 40428737, 2025). "Through this large-scale retrospective analysis of a joint research network, researchers have discovered that patients with low albumin levels face a significantly increased risk of cardiovascular disease." (PMID 38655495, 2024). "Conversely, low albumin levels have been linked to cardiovascular diseases and an increased risk of mortality." (PMID 39685462, 2024). "In a recent prospective study of 1070 patients with cardiovascular pathology, an association was found between low albumin levels and long-term mortality in cardiovascular disease." (PMID 38541144, 2024). "Our study demonstrates a significant association between serum albumin levels and cardiovascular disease, underscoring the crucial role of low serum albumin as a predictive factor in patients with cardiovascular disease." (PMID 38580915, 2024). "Albumin is inversely related to inflammation and low albumin level also has been recognized as a risk factor for cardiovascular disease." (PMID 38559668, 2024). "Arterial thrombotic events were found to be associated with factors such as age, cardiovascular disease, levels of white blood cells, D-dimers, and albumin in the blood." (PMID 38672130, 2024). "Studies suggest that lower levels of albumin are associated with an increased risk of mortality from cardiovascular disease." (PMID 39087072, 2024). "Serum albumin, known for its affordability and convenience in clinical testing, holds promise in improving the prognosis of cardiovascular diseases by elucidating its potential causal relationship." (PMID 38580915, 2024). "In a study on longitudinal aging conducted in Amsterdam, among 713 respondents, after adjusting for potential confounding factors, higher levels of albumin were associated with a lower risk of cardiovascular disease (RR 0.88, 95%CI: 0.79, 0.98)." (PMID 39114122, 2024). "These included BMI ≤ 23.0 kg/m2, two underlying comorbidities (cardiovascular diseases and immunocompromised state), and three laboratory parameters on day 14 of MV (platelet count < 150 × 103/μL, PaO2/FiO2 ≤ 200 mmHg, and albumin ≤ 2.8 g/dL)." (PMID 38399567, 2024). "Red cell distribution width to albumin ratio (RAR) has been demonstrated to be associated with the risk of cardiovascular diseases." (PMID 38331757, 2024).
cardiovascular disease (continued). "They found that the most common risk factors reported included older age, cardiovascular disease, lower serum albumin and late referral." (PMID 39669010, 2024). "Urine albumin-to-creatinine ratio (uACR) is an important measure of kidney function and an independent risk factor for cardiovascular disease." (PMID 37868129, 2023). "Short stature in adulthood was reported to be positively associated with cardiovascular disease, and the incidence of cardiovascular disease was positively correlated with low serum albumin levels." (PMID 37700384, 2023). "Low levels of serum albumin and reductions in ROS-scavenging properties have been linked to poor cardiovascular disease outcomes in humans; in elephants, EEHV-HD also affects cardiac function." (PMID 37174585, 2023). "Previous studies have found that low albumin levels are associated with increased cardiovascular disease or mortality." (PMID 37622119, 2023). "Elevated urinary albumin excretion independently and continuously predicts an increased risk of cardiovascular disease, even at levels below the threshold for the diagnosis of microalbuminuria." (PMID 37047877, 2023). "In our study, we defined CAR as the ratio of hsCRP to albumin, based on prior research confirming hsCRP as being more strongly associated with cardiovascular disease prognosis than CRP." (PMID 37649485, 2023). "In the <25 kg/m2 BMI group, age, BMI, WHtR, cardiovascular disease, MS, eGFR, hemoglobin level, albumin level, CRP level, triglyceride level, and all-cause mortality increased with TBF%, but progression to ESRD and Upcr decreased." (PMID 36185692, 2022). "In 2020, another Chinese study showed that urinary albumin-creatinine ratio (UACR) within the normal range (less than 30 mg/g) would also increase the risk of cardiovascular disease." (PMID 34983421, 2022). "Albumin, an important component of fluid balance, is associated with kidney, liver, nutritional, and cardiovascular diseases (CVD) and is measured by blood tests." (PMID 35770216, 2022). "BMI and serum albumin are important indicators for evaluating the risk and prognosis of cardiovascular disease." (PMID 34996387, 2022). "There is evidence that serum albumin is associated with an increased risk of cardiovascular disease mortality in various clinical conditions and in patients who undergo TAVR." (PMID 35244369, 2022). "Serum albumin levels have been reported to be inversely associated with the cardiovascular disease risk and aging, supporting its possible causal relationships with the oxidative stress-related status and diseases." (PMID 35864124, 2022). "Age, cardiovascular disease, intensive care unit treatment, white blood cells, D-dimer, albumin and troponin blood levels were associated with thrombotic events." (PMID 34218413, 2021). "MLRA revealed four risk variables associated with 72-hour mortality—age, albumin, inorganic phosphate, and cardiovascular disease—with a predictability of 0.829 in C-statistics." (PMID 33606735, 2021). "Several studies show that even a level of urine albumin/creatinine ratio (UACR) within the normal range (below 30 mg/g) increases the risk of cardiovascular diseases." (PMID 32076606, 2020). "We found that a low p-albumin concentration at baseline was a risk marker for total mortality, as well as mortality in malignancies and cardiovascular disease after 10–14 years, especially at younger ages." (PMID 33226880, 2020). "Lipoproteins containing apolipoprotein B modify associations of elevated urinary albumin excretion (UAE) with cardiovascular disease (CVD)." (PMID 30813431, 2019). "Elevated urinary albumin excretion (UAE) is well known to be associated with cardiovascular disease (CVD) risk." (PMID 30813431, 2019). "It is well established that increased urine albumin is an independent risk factor in kidney and cardiovascular disease, and the reduction of albuminuria has been shown to reduce cardiovascular events." (PMID 30732594, 2019).